EGFR (epidermal growth factor receptor)
Diseases named in the same sentence as EGFR in open-access papers (continued):
Sharing a sentence is not in itself a finding about the gene and the disease.
tumor (continued). "An anti-EGFR mAb (cetuximab) is used in patients with colorectal or head and neck cancers to inhibit tumor cell proliferation." (PMID 34572013, 2021). "In a recent study, it was found that tumor uptake and tumor visualization performed with anti-EGFR coated gold nanoparticles with 20 nm size showed increased tumor uptake, whereas the same gold nanoparticles of 50 nm size illustrated excellent CT contrast." (PMID 34200251, 2021). "In many tumor types, including TC, increased EGFR expression or activity initiates the tumor cell progression." (PMID 34202358, 2021). "Uptake was partly EGFR specific, as demonstrated by significantly lower tumor uptake upon co-injection of unlabeled cetuximab (4.76 ± 0.3%IA/g versus 2.94 ± 0.79%IA/g, p = 0.0201)." (PMID 33498707, 2021). "Activation of EGFR and the downstream signaling network impacts multiple cellular processes including proliferation, survival, invasion, and metastasis, facilitating tumor progression." (PMID 33537094, 2021). "Further, compared with analysis results from tumor histologic samples, the sensitivity of BWF in EGFR mutation detection was 92.5% and the concordance rate was 97.9%." (PMID 33828971, 2021). "To further dissect the importance of PIR-B on anti-tumor immunity, we transplanted the same EGFR-LLC cells into immunodeficient NSG mice to evaluate its effect on tumor biology." (PMID 33537094, 2021). "Conversely, as also observed in patients, the crizotinib (anti-MET TKI) and osimertinib combination improved survival and reduced tumor burden in EGFR/MET mice, further validating the model’s value for preclinical studies." (PMID 34298655, 2021). "TGFA has been previously confirmed as a crucial oncogenic mediator and promotes tumor cell growth via the TGF-α/EGFR signaling pathway." (PMID 34079795, 2021). "Given the fact that targeting EGFR has demonstrated therapeutic benefit in other neoplastic diseases, our results support the possibility of acting on this receptor." (PMID 34399807, 2021). "The advantage of nimotuzumab over other anti-EGFR Mab is its benign adverse effect profile as it requires bivalent binding for stable attachment, leading to selective binding to tumor cells that overexpress the EGFR level." (PMID 34104833, 2021). "Our results are consistent with previous studies which reported that increased the number of EGFR in tumor was associated with DOX resistance, and that combination of DOX with anti-EGFR therapy enhanced DOX effects against EGFR overexpressed tumor xenografts." (PMID 33509300, 2021). "We elucidated that the interaction of specific agonist G1-triggered GPER activation and its downstream EGFR/ERK signaling plays a key role in decreasing the tumor viability of HCC." (PMID 33767999, 2021). "We recommend further preclinical studies and consideration of clinical investigation of scheduled anti-EGFR therapies combined with taxanes for ESCC patients with tumours expressing high EGFR by IHC and/or EGFR CNG." (PMID 33169187, 2021). "While fibroblast cells, like tumor cells, expressed EGFR and FGFR1, they also exclusively expressed higher levels of the receptors LRP1, PDGFRs, and PLXND1 in both patients." (PMID 34459128, 2021). "The degree of response to EGFR inhibitors measured by tumor shrinkage varies widely among HNSCC patients, and the biological mechanisms that underlie therapeutic heterogeneity amongst HNSCC patients remain ill-defined." (PMID 33485341, 2021). "Only with co-application of rituximab (in an EGFR-positive xenograft model), tumor growth was reduced and led to complete tumor eradication and long-term survival (>250 days) in 25% of treated animals." (PMID 34729396, 2021).
tumor (continued). "Most importantly, generated IgG-like bsAbs facilitated significant NK cell-mediated lysis of EGFR-overexpressing A431 tumor cells as well as a robust release of proinflammatory cytokine interferon-γ (IFN-γ)." (PMID 35087526, 2021). "VEGF, a HIF-1α target gene, is modulated by activation of several receptor tyrosine kinases, and EGFR inhibition has been found to decrease VEGF expression in many tumor types." (PMID 34381712, 2021). "This study showed that EGFR expression in tumour tissue mimicked that in patients and correlated with the response to therapy." (PMID 33801782, 2021). "Using a novel inhibitor of RAC1B splicing, we demonstrate enhanced sensitivity to EGFR inhibition following RAC1B depletion in cetuximab-resistant human tumour organoids." (PMID 33879799, 2021). "Considering the complex picture of EGFR status and the high frequency of mutated transcripts, we explored the NBI‐ddPCR pipeline in selected EV sub‐populations, virtually deriving from tumor cells by assuming the presence of EGFR receptor on their surface." (PMID 33942501, 2021). "Monoclonal antibodies, such as cetuximab and panitumumab, target the extracellular domain of EGFR to block ligand binding and intracellular signaling, thus inhibiting tumor cell proliferation, angiogenesis, and metastasis." (PMID 34884633, 2021). "In tumours and EGFR mutant cell lines, we further identified that CDCA3 correlates with sensitivity to TKI." (PMID 34572879, 2021). "In all patients with tissue−ctDNA+ tumors, tumor tissue samples were obtained before the initiation of anti-epidermal growth factor receptor (EGFR) therapy, whereas plasma samples were collected after progression on anti-EGFR therapy." (PMID 34764486, 2021). "The antibody promotes the inhibition of EGFR signaling, thereby reducing a factor that is responsible for tumor development and progression." (PMID 34452282, 2021). "EGFR is a very important target in cancer therapy, being a central regulator of tumor progression in a variety of human cancers, including mCRC, one of the leading causes of cancer-related death worldwide." (PMID 34071597, 2021). "Fluorescent analysis of the dissected tumor tissues showed that BJ extracts reduced fluorescent EGFR and its phosphorylated forms." (PMID 35582384, 2021). "The antiproliferative capabilities of SH-1028 and Imp3 were compared with osimertinib using a number of tumor cell lines harboring either the wild-type or mutant forms of EGFR." (PMID 33986687, 2021). "Its observed activity in an EGFR-activated brain metastasis tumor model is also corroborated by outputs from bioinformatics analyses." (PMID 33889302, 2021). "This newly engineered CAR, designated CAR-TEAM, can produce TEAM (T-cell Engaging Antibody Molecule) that targets wild type EGFR, and like BiTE, binds both EGFR on the tumor cells at the local site and CD3 on the T cells." (PMID 34332618, 2021). "Cattle-derived chimeric antibodies were potent in inducing antibody-dependent cell-mediated cytotoxicity (ADCC) against EGFR-overexpressing tumor cells with potencies (EC50 killing) in the picomolar range." (PMID 34759924, 2021). "The EGF receptor (EGFR) has been extensively studied in tumor biology and recently a role in cardiovascular pathophysiology was suggested." (PMID 34168192, 2021). "This has been reported in NSCLC patients with EGFR mutations and ALK rearrangements, which are also associated with low tumor neoantigen load." (PMID 34208113, 2021). "In this study, we report that a bispecific single domain antibody (VHH) that targets CD16 (FcRγIII) on NK cells and the epidermal growth factor receptor (EGFR) on tumor cells can be used to target and enhance cytolysis of cancer cells." (PMID 34771609, 2021). "This analysis revealed that EGFR-based active targeting was effective in ensuring an enhanced DOX delivery to tumor sites, thereby augmenting the antitumor efficacy of this chemotherapeutic drug while decreasing its off-target toxicity." (PMID 34298600, 2021).
tumor (continued). "The EGFR inhibitor erlotinib exhibits tumor-preventive efficacy in individuals with familial adenomatous polyposis, a syndrome caused by inheritance of a mutant allele of APC." (PMID 34513688, 2021). "Gefitinib is a selective EGFR tyrosine kinase inhibitor which hinder tumor growth, metastasis, and angiogenesis, and increase tumor cell apoptosis." (PMID 34059647, 2021). "They showed that exosomes containing EGFR are formed thanks to the activity of AnxA1, inducing tumor specific Tregs." (PMID 34571894, 2021). "For example, the donor cells were engineered to express EGFR binding peptides on EV surface, and the modified EVs efficiently delivered let-7a specifically to EGFR-expressing tumor tissues." (PMID 34803608, 2021). "Combination treatment upregulated the expression of GSDME-N and cleaved caspase-1 in tumor tissues, but downregulated the expression of p-EGFR." (PMID 33472170, 2021). "EGFR‐targeted therapies, such as cetuximab, competitively block the binding of endogenous EGF ligand to the EGFR, which blocks the receptor‐dependent signal transduction pathways for the growth and survival of tumor cells." (PMID 33540470, 2021). "Overall, VEGF and EGFR play essential roles in tumor growth, invasion, metastasis, and angiogenesis." (PMID 35069035, 2021). "Although osimertinib combined with crizotinib therapy showed dramatic tumor shrinkage in both the primary tumor and bone metastasis to an EGFR T790M-mutant NSCLC patient with MET amplification, the progression-free survival (PFS) was only two months." (PMID 34397683, 2021). "Within the two cohorts, the uncommon EGFR mutation-positive showed a significant difference in serum carcinoembryonic antigen (CEA) and tumor grade (P < 0.05)." (PMID 34976788, 2021). "In the study, antigens that entailed the risk of off-target toxicity in the case of systemic administration (i.e., EGFR) were successfully targeted locally in the tumor microenvironment." (PMID 34177890, 2021). "Several studies on EGFR-dependent expression of PD-L1 extended the spectrum beyond the JAK/STAT signaling pathway in a variety of human tumor entities." (PMID 33718186, 2021). "Future work is needed to further understand the biologic underpinnings of the clinical correlation between NLR and prognosis and to identify novel strategies to target the EGFR tumor microenvironment in patients with high NLR." (PMID 33804721, 2021). "It was revealed that EGFR is a direct target of miR-141, and EGFR was found to enhance tumor growth, invasion, and metastasis." (PMID 34208375, 2021). "The validation cohort shows that there is no significantly different distribution between the WT and the EGFR groups in age, tumor stage or N-stage." (PMID 34941646, 2021). "Tumor uptake in the blocked group was significantly (p < 0.005) reduced compared with the unblocked group, indicating highly EGFR specific accumulation of [66Ga]Ga-DFO-ZEGFR:2377 in EGFR-expressing tumors." (PMID 33672373, 2021). "In the PTEN-deficient TNBC cell line MDA-MB-468, a new potential therapeutic strategy for combination targeting of both EGFR and PI3Kβ was suggested to induce anti-tumor activity." (PMID 34681198, 2021). "For example, patients with CMS2 tumours preferentially benefit from anti-epidermal growth factor receptor (EGFR) and anti-vascular endothelial growth factor (VEGF) therapy." (PMID 33879799, 2021). "For example, miR-21 can mediate ROS production by enhancing KRAS and epidermal growth factor receptor signaling, thereby promoting tumor development." (PMID 34804366, 2021). "We also performed in vitro off‐target analysis using three human EGFR– tumor cell lines (JeKo‐1, Jurkat, and EL‐4)." (PMID 33540470, 2021). "We included a cohort of 20 NSCLC patients with EGFR WT tumor tissues and systematically performed molecular EV‐RNA and circulating tumor DNA analyses with clinical data statistics and biophysical profiles of EVs." (PMID 33942501, 2021).
tumor (continued). "Most importantly, engineered cattle-derived bispecific common light chain molecules elicited potent NK cell redirection and consequently tumor cell lysis of EGFR-overexpressing cells as well as robust release of proinflammatory cytokine interferon-γ." (PMID 35087526, 2021). "Such targets include vascular endothelial growth factor (VEGF) and epidermal growth factor receptor (EGFR), the latter of which promotes tumor cell growth." (PMID 34447749, 2021). "In vitro functional studies of the new USP8 G664R variant were performed in mouse corticotroph tumor cells AtT-20, bearing wild-type USP8 and endogenously expressing EGFR." (PMID 34439178, 2021). "Secondly, the tumor cell-extrinsic factors from the Matrigel activate ErbB family receptors, EGFR and HER2." (PMID 34066157, 2021). "EGFR signaling has been shown to regulate different processes involved in tumor development, such as proliferation, migration and invasion." (PMID 33946151, 2021). "In PDAC, EGFR is involved in the activation of pathways that contribute to tumor proliferation, metastasis, malignant transformation, survival, and drug resistance 11,20." (PMID 34522225, 2021). "Research in BC showed that GRB2 is a pivotal molecule in tumor growth and downregulation of its expression can lead to inhibition of breast cells with high EGFR and ERBB2 expression levels." (PMID 34679042, 2021). "Our discovery of tumor microenvironment controlling the sensitivity to T-DM1 through upregulating EGFR activity provides an opportunity to develop a new therapeutic strategy to overcome primary resistance to T-DM1." (PMID 34066157, 2021). "CD44v6 can promote tumor cell proliferation, while CSCs with high expression of EGFR-211 and EGFR-201 show low invasion and high proliferation features." (PMID 33990550, 2021). "EGFR and KRAS mutation status discordance between primary tumor and LCBM occurs in approximately 10% and 13% of patients, respectively." (PMID 35201504, 2021). "α-Curcumin can block tumor growth by targeting epidermal growth factor receptor (EGFR) among others." (PMID 34360915, 2021). "Serial mid-treatment biopsies of tumor tissue and ctDNA at baseline and progression to detect histologic transformation should be incorporated in all future clinical trials with EGFR TKIs, whenever possible." (PMID 34572868, 2021). "Agents that target EGFR signalling signalling, such as gefitinib, erlotinib, and icotinib, have already received approval for the treatment of tumours." (PMID 34369236, 2021). "Bone marrow cells inhibit CD8+ T cell anti-tumor activity by inducing expression of PD-L1 by tumor cells in an epidermal growth factor receptor (EGFR)/mitogen-activated protein kinase (MAPK)-dependent manner." (PMID 34439378, 2021). "In a Canadian validation study of plasma EGFR T790M testing, plasma testing showed more T790M‐positive results (62%) than tumor biopsy alone (49%), with 75% sensitivity using highly sensitive methods such as ddPCR, next‐generation sequencing, and RT‐PCR." (PMID 33270375, 2021). "DOK2 was demonstrated to be a tumor suppressor, where its overexpression inhibited the tumor-forming ability of EGFR mutant LUAD cells and its loss led to oncogenic EGFR-driven tumorigenesis in vivo." (PMID 34944063, 2021). "Our present study found that ILT4 inhibition reconfigured the immunosuppressive and tumor-promoting microenvironment, and repressed the progression of EGFR mutant NSCLC." (PMID 33537094, 2021). "A Japanese group of researchers reported that the high expression of EGFR and p-EGFR was correlated with tumour invasion, however high expression was unrelated to tumour stage, lymph node or distant metastasis." (PMID 35002542, 2021). "On the one hand, miR-7 targets and downregulates tumorigenic factors in tumour-associated signalling pathways such as PA28γ, EGFR, PAK1, ACK1 and PIK3CD, demonstrating the crucial role of miR-7 in tumour suppression." (PMID 33390839, 2021).
tumor (continued). "Clinically approved drugs, including vascular endothelial growth factor (VEGF) inhibitors and epidermal growth factor receptor (EGFR) inhibitors, are often accompanied by drug resistance and tumor recurrence." (PMID 33634965, 2021). "This NKp46/Fc/EGFR TriKE shows remarkable advantages in augmenting NK infiltration in tumor tissue and promoting their anti-cancer efficacy over anti-EGFR mAb therapies such as cetuximab." (PMID 35008589, 2021). "Collectively, our novel findings demonstrate that anti-EGFR/VEGFR2 BsAb inhibits tumor growth via multiple mechanisms of action and warrants further investigation as a targeted antibody therapeutic for the treatment of TNBC." (PMID 33804477, 2021). "In the current study, we report for the first time the direct interaction of EGFR with the tumor suppressor CSMD1, which leads to attenuation of EGFR signaling due to altered trafficking of the receptor." (PMID 34404439, 2021). "Tumours with a higher number of genomic clonal subpopulations that are not EGFR-driven are less likely to respond significantly to monotherapy with an EGFR inhibitor." (PMID 33169187, 2021). "Compared with conventional means of sentinel node identification in which the gamma tracer is injected directly into tumor tissue, anti-EGFR-labeled tracers are injected systemically." (PMID 34002555, 2021). "Epidermal growth factor receptor (EGFR) signaling pathway is activated in various neoplasms, and EGFR-tyrosine kinase inhibitors (EGFR-TKIs) are used as targeted therapy in these cancers." (PMID 34021125, 2021). "It is reported that overexpression of heparanase also stimulates the phosphorylation of EGFR in different tumor cell lines and inhibiting heparanase expression results in the reduction of EGFR phosphorylation." (PMID 34681753, 2021). "Apparent equilibrium dissociation constant (Kd) of C-7 and 7-D binding to both CD16 on CD56+CD3− NK cells or NK16+ NK92 and EGFR on the A431 tumor cell line." (PMID 34771609, 2021). "This indicates that the presence of the EGFR aptamer on the PNP surface was able to concentrate the Cis-Pt payload at the tumor site, thereby enhancing the anticancer activity of the drug." (PMID 34294133, 2021). "EGFR activity orchestrates multiple cellular processes responsible to tumor growth and progression, such as proliferation, metastasis, invasion and angiogenesis." (PMID 34641511, 2021). "Over-expression of the lnc-Epidermal Growth Factor Receptor (EGFR) regulatory T cells (Tregs) has been related with tumor size and levels of EGFR/Foxp3." (PMID 33968749, 2021). "Current evidence from in vitro and in vivo studies on chemopreventive phytochemicals that target NOX, EGFR, or both, as major regulators of skin carcinogenesis will also be discussed." (PMID 34943012, 2021). "In ESCC, up-regulated DNA methyltransferase 1 contributes to tumor growth through ADAM9-mediated epidermal growth factor receptor (EGFR)-AKT signaling." (PMID 34671207, 2021). "Together, these studies highlight the broad range of pathways that affect EGFR signaling in NSCLC tumor cells." (PMID 34944063, 2021). "Studies have shown that PE38 has a toxic effect on EGFR-expressing tumor cells, both in vitro as well as against tumors in a mouse model." (PMID 33738260, 2021). "We characterized the kinase-signaling network, where we identified LCK and EGFR as interconnected, down-regulated kinases and the tumor suppressors ATM and CDK2 as interconnected, up-regulated kinases." (PMID 34238254, 2021). "For anti-EGFR antibody-coated GNPs in a tumor model in mice, a labeling efficiency of 3.4 × 103 GNPs per tumor cell, equivalent to 10.52 pg gold/cell, was reached in vitro." (PMID 34830917, 2021).